VLDLR-AS1 (VLDLR antisense RNA 1)
Synonyms: lincRNA-VLDLR; linc-VLDLR
Gene: Long non-coding RNA gene on chromosome 9 (2,301,072 to 2,622,457, reverse strand). Ensembl gene ENSG00000236404.
Diseases named in the same sentence as VLDLR-AS1 in open-access papers:
VLDLR-AS1 is named in the same sentence as 2 diseases in open-access papers, as found by Europe PMC text mining. Sharing a sentence is not in itself a finding about the gene and the disease.
VLDLR-AS1 shares sentences with these, for which no sentence is quoted: hepatocellular carcinoma (2 papers); tumor (1).